CD68 (CD68 molecule)
Diseases named in the same sentence as CD68 in open-access papers (continued):
Sharing a sentence is not in itself a finding about the gene and the disease.
tumor (continued). "To investigate the immunogenicity of HR-d PDAC, we used multiplex immunohistochemistry (IHC) to compare the density and spatial distribution of CD8+ cytotoxic T-cells, FOXP3+ regulatory T-cells (Tregs), and CD68+ tumor-associated macrophages (TAMs) in HR-d versus HR/MMR-intact PDAC." (PMID 35547873, 2022). "Kaplan–Meier survival analysis revealed a significant association between stromal CXCL8 and CD68+ cell density, with a significant reduction in survival of patients whose tumours were high for both compared to those high for one and low for both markers (HR = 1.880, 95% CI: 1.299–2.720, p = 0.001)." (PMID 35879507, 2022). "Finally, proximity profiling of total CD68 cells near PD-L1-positive tumor cells similarly shows a significant association with elevated cytoplasmic Kaiso and LC3A/B compared to nuclear Kaiso and Race." (PMID 33526872, 2021). "However, the density of M2-type tumor-associated macrophages with CD68+ CD163+ phenotypes was significantly higher (P < 0.01) in tumors from DPP-4i users." (PMID 36860286, 2021). "Furthermore, VISTA was expressed at a significantly higher level in CD68+ tumor-associated macrophages." (PMID 33237432, 2021). "Cells of innate immunity, mainly tumor-associated macrophages (TAMs) can be polarized into antitumoral M1 macrophages, expressing CD68, and protumoral and immunosuppressive M2 macrophages, characterized by coexpression of CD68 and CD163." (PMID 33494389, 2021). "The presence of tumor-infiltrating immune cells, here represented as macrophages characterized by the markers CD68, CD163, and CCL2, was associated with a superior prognosis, and chemotherapy may not add an advantage for prognosis." (PMID 33467469, 2021). "Similarly, elevated levels of both cytoplasmic Kaiso and LC3A/B were associated with increased proximity of PD-L1-positive CD68 cells near tumor compared to insignificant association with nuclear Kaiso and Race." (PMID 33526872, 2021). "Moreover, VISTA was expressed at significantly higher levels in CD68+ tumor-associated macrophages than in tumor-infiltrating CD3+ T or CD19+ B cells." (PMID 33237432, 2021). "Similarly, our analysis identified high CD68+ TAM/tumor cell clustering as having a strong association with worse OS." (PMID 33882057, 2021). "High KLK6 levels in tumour and CD68+ cells were linked to shorter survival." (PMID 34439122, 2021). "Furthermore, when CD68+ cell density and tumor/CD68+ cellular clustering were included as covariates in the same Cox regression, tumor/CD68+ clustering had a stronger association with OS." (PMID 33882057, 2021). "High numbers of CD68+ TAMs in the tumor stroma were significantly associated with larger tumor size and positive nodal metastasis, whereas high numbers of CD163+ TAMs in the tumor stroma were significantly associated with positive vascular invasion, nodal metastasis, and molecular subtypes." (PMID 33968034, 2021). "In addition, while CD68 + macrophages were found to closely associate with tumor cells, PD-L1 + macrophages were found to have the closest interaction with PD-L1 + tumor cells." (PMID 33633208, 2021). "When the xCell scores were estimated, the tumor stage was significantly associated with the number of macrophages and that the number of infiltrating CD68-, CD163- and CD204-positive macrophages were significantly associated with tumor heterogeneity as evaluated by TA." (PMID 34244567, 2021). "The presence of tumor-infiltrating immune cells, characterized by the markers CD68, CD163, and CCL2, was associated with a superior prognosis, and chemotherapy may not add an advantage for prognosis." (PMID 33467469, 2021). "CD68 is a major biomarker for the quantification of tumor-associated macrophages (TAMs)." (PMID 34025640, 2021). "Likewise, our study results showed that high CD68 expression in tumor stroma is associated with good prognosis." (PMID 33228719, 2020).
tumor (continued). "We hypothesize that this time-dependent effect could be related to different polarization patterns of tumor-associated macrophages because CD68 is recognized as a pan-macrophage biomarker." (PMID 33042787, 2020). "The correlation between LGALS3 expression and the infiltration of multiple intra-tumoral immune cell types, including B cells (CD20), T cells (CD4 and CD8), macrophages (CD68), and M2 tumor-associated macrophages (CD163), was evaluated by Spearman correlation analysis." (PMID 32528967, 2020). "For example, our study used CD68 as a well-validated marker for tumor associated macrophages." (PMID 32866185, 2020). "High counts of CD3 + and CD68+ cells at the IM and CT were associated with smaller tumor size." (PMID 33211709, 2020). "Both luminal B and TN tumours showed associations with CD68 + macrophages." (PMID 31819174, 2020). "We investigated the link between TAMs and tumor proliferation and found a strong positive association between the density of CD68+/CD163+ TAMs in the stroma and proliferation of tumor cells as determined by Ki67 staining, but no such association was detected in parenchymal or luminal areas." (PMID 32190817, 2020). "Furthermore, VISTA expression was higher in CD68+ tumor-associated macrophages (TAMs) than in CD4+ T cells, CD8+ cytotoxic T cells or CD20+ B cells." (PMID 33250890, 2020). "Due to loss of material or low tumor content, the expression of CD68 could be evaluated in 162/174 (93.1%) of the total group of patients." (PMID 33194593, 2020). "All tumor-associated macrophages independent on their phenotype seem to express CD68." (PMID 32884895, 2020). "Thus, a study of 160 patients with stage IIIB and IV colon carcinoma demonstrated that high density of CD68+ macrophages in invasive front of tumor was associated with higher 5-year survival rate and lower hepatic metastasis." (PMID 33194645, 2020). "The immune checkpoint marker TIM‐3, in addition to its negative association with sTILs %, also inversely correlated with CD68 staining grade and with whole tumor density of CD8+ and CD20+ cells, while IL‐1α only showed a significant inverse association with CD8." (PMID 33024560, 2020). "In the stepwise multivariate analysis, the volume of tumor with elevated Kep (P = .001), CD68+ macrophage density (P = .01), and size of tumor vessels (P = .01) were found to be independently associated with plasma cfDNA concentration (adjusted R2 of the final model = 0.62)." (PMID 32140683, 2020). "Moreover, CD163+/CD68+ ratio in tumor front was also significantly associated with EMT program and CTC amount." (PMID 33194645, 2020). "The risk model showed that the expression level of CD68 was positively correlated with the risk score, which was consistent with the current literature reports, suggesting that tumor-associated macrophages might be involved in tumor progression in pRCC." (PMID 32536823, 2020). "Moreover, VISTA expression was higher in CD68+ tumor-associated macrophages (TAMs; 32.58%) than in CD4+ T cells (4.97%), CD8+ cytotoxic T cells (4.48%), or CD20+ B cells (1.46%)." (PMID 33250890, 2020). "The effectiveness of non-CTCs demarcation can be strengthened by combining targeting of CD45 with other biomarkers, like those specific for myeloid cells (CD11b), tumor-associated macrophages (CD68), erythrocytes (CD235a), endothelial cells (CD146), and hematopoietic stem cells (CD34)." (PMID 31185699, 2019). "Tumor-associated macrophages (TAMs) may also play a role in the tumor microenvironment, but studies on (CD68+) TAM infiltrate as a biomarker in the neoadjuvant setting are scarce." (PMID 30868392, 2019). "Increased tumor infiltration of CD68+ cells were associated with higher stage disease." (PMID 31905599, 2019). "Moreover, we identified significant coherences between PD-L1 expression in tumor-associated lymph follicles and the local abundance of tumor-associated macrophages (TAMs) (CD68+, CD163+)." (PMID 30899426, 2019).
tumor (continued). "CD68 was considered as a marker of tumor associated macrophages elevated approximately 100-fold." (PMID 31905766, 2019). "Moreover, high CD68+ macrophage density and advanced tumor stage are associated with shorter recurrence-free and overall survival of HNSCC patients." (PMID 29541395, 2018). "Besides providing a pro-inflammatory status by interaction with DCs, NK and CTL, iNKT have also been found to be able to control tumor growth by killing tumor supportive IL-6-producing CD1d+ CD68+ tumor associated macrophages (TAM)." (PMID 30298063, 2018). "Furthermore, high PD-L1 was also associated with a more “anti-tumour” M1-like phenotype as evidenced by the significantly higher gene expression signature score (p=<0.0001) and a significantly lower ratio of CD68/CD8 gene expression (p= <0.0001)." (PMID 30651729, 2018). "In addition to its expression on TIL and tumor cells, PD-L1 is also found on other immune cells, CD68+ tumor-associated macrophages and myeloid cells, such as follicular dendritic cells resident in TLS." (PMID 29163490, 2017). "Macrophage activity during tumor initiation and early stage progression may depend on lesion histopathology, as MRI studies have shown that the infiltration of CD68+ cells is strongly associated with high grade comedo DCIS lesions." (PMID 28881599, 2017). "Also, to investigate the degree of treatment-induced inflammation that potentially can cause variation in 18F-FDG tumor uptake, we performed immunohistochemical staining for macrophage marker CD68." (PMID 28542311, 2017). "However, the pooled HR of 4 studies showed that high density of CD68+ TAMs in the tumor islet predicted better OS, while the pooled HR of 6 studies showed that high density of CD68+ TAMs in the tumor stroma was associated with poor OS." (PMID 27144518, 2016). "Tumor stroma CD68 density could only identify low-risk group and high-risk group at TNM stage I, II and III." (PMID 26771842, 2016). "We measured the expression of HMGB1 and CD68 in tumoral and peritumoral liver tissues after curative resection and assessed the impacts of the tumor-associated macrophage (TAM) count and HMGB1 expression on clinicopathologic characteristics, overall survival (OS), and recurrence-free survival (RFS)." (PMID 27836008, 2016). "We also find that IDO1 was produced by tumor cells and by tumor-associated interstitial cells that may be CD68+ macrophages or may be other “round” cells observed in these sections, including non-macrophage myeloid derived cells." (PMID 27572319, 2016). "Tumor-associated macrophages were assessed based on the expression of CD68." (PMID 26413839, 2015). "Interestingly, strong nuclear staining of β-catenin GC cells was associated with CD68+ macrophages in the tumor lesions, especially in front of the tumor invasion." (PMID 26226629, 2015). "The tumor was positive for CD68, a macrophage-specific marker, indicating a pronounced infiltration of macrophages; accumulating evidence has linked tumor-associated macrophages and tumor progression." (PMID 25120721, 2014). "Most papers in the meta-analysis used CD68 as a marker for tumor-associated macrophages (TAMs)." (PMID 25144454, 2014). "Recently, tumor-associated macrophages (TAMs) in lesional tissues have been shown to be a strong prognostic indicator of cHL by gene expression profile analysis and subsequent immunohistochemical detection using CD68 and CD163 as markers." (PMID 24489836, 2014). "Interestingly, expression of the macrophage marker CD68 was specifically associated with tumor epithelium-specific STAT1 expression." (PMID 24725474, 2014). "The analysis of CD68+ tumor-associated macrophages and IHC staining data were verified by qRT-PCR, which demonstrated that CD68 expression in the poor outcome group was 77-fold greater than in the good outcome group, and 224-fold greater than in normal lymph nodes." (PMID 23988031, 2013).
tumor (continued). "While patients in this group may benefit from analysis of the tumor-associated macrophage marker CD68, which can be used to predict adverse outcomes of cHL, the prediction is controversial." (PMID 23988031, 2013). "Interestingly, the recruitment of the CD68 positive cells, which are tumor-associated macrophages (TAMs), is seen mainly among the invasive tumor cells and to a lesser extent in the associated stroma." (PMID 23741308, 2013). "Therefore, we evaluated the number of CD68+ tumor-associated macrophages in the good and poor outcome groups." (PMID 23988031, 2013). "Thus, we found that a high CD68/(CD3+CD20) ratio (>0.5) at the invasive front is associated with tumor aggressiveness and poor prognosis in patients." (PMID 23300781, 2012). "It appears that the association of CD68+ TAMs with hypoxia is tumor dependent." (PMID 22888475, 2012). "Furthermore, expression by tumour-associated macrophages was observed, as determined by double-staining with the monocyte/macrophage marker, CD68." (PMID 20969772, 2010). "For histology and CD68 (P = 0.010), according to Z-tests with Bonferroni correction, centroblastic tumours were associated with low expression (76.7% vs. 43.5%); in comparison, high-grade tumours exhibited a greater association with high expression (13% vs. 0%)." (PMID 40599139, 2025). "Furthermore, significant correlations emerged among FAP + CAFs, TILs, and CD68 + cells, and the co-occurrence of elevated FAP + CAFs, T-cytotoxic (CD8 +), T-regulatory (CD4 + FOXP3 +) cells, and macrophages (CD68 +) at the tumor center were independently associated with worse CSS." (PMID 39751643, 2025). "However, it should be noted that CD68+ expression is also characterized by Tumor-associated macrophages (TAM), which may function as an immune suppressor and contribute to GBM progression in the tumor microenvironment resulting in a worsened prognosis." (PMID 40807266, 2025). "Moreover, the number of CD68+ TAMs in TN of KT tissues was an independent risk factor affecting patient OS, whereas tumor resection scope might be an independent risk factor affecting patient PFS." (PMID 36910657, 2023). "The complexity of CD4+ T lymphocytes (presumably Th2 or Tregs or both) in conjunction with CD8+ T lymphocytes and CD68+ tumor-associated macrophages (TAMs) were also reported that could be predictive of overall survival (OS) and relapse-free survival (RFS) in node-positive human BC." (PMID 37835465, 2023). "The presence of higher than median CD68+MRP8-14+CD86neg M1 macrophages in the tumor center was associated with poor overall survival (median 2.34 years) compared to cases with lower than median M1 macrophages at the tumor center (median 6.41 years) in univariate analysis." (PMID 37637998, 2023). "In addition, the high CD8 + mTILs/CD68 + TAMs ratio was associated with a higher tumor grade." (PMID 37428418, 2023). "In addition, the mutation landscape of CD68 in pan-tumor types was also observed." (PMID 35550532, 2022). "Hence, we subsequently investigated whether F3 treatment also increased the infiltration of T cells with decreased presence of tumor-associated macrophages (TAMs) as defined by CD68 positivity." (PMID 35972917, 2022). "Our working hypothesis is that the presence of tumor-infiltrating immune cells, here represented as macrophages characterized by the markers CD68, CD163, and CCL2, could be associated with a better prognosis, but that chemotherapy may not add an advantage for prognosis." (PMID 33467469, 2021). "Similarly, our results found that tumor nest-associated CD68+ macrophages and tumor stroma-associated CD68+ macrophages have different prognostic values for patients with GC, which suggests that macrophages infiltration at the CT or MI have different TME roles." (PMID 34926251, 2021).
tumor (continued). "Recently, in stage III CRC, higher CD68+ macrophage infiltration has been correlated with decreased overall survival; on the contrary, another study showed that CD68+ macrophage infiltration at the tumor invasive front associates to increased overall survival in patients treated with 5-FU." (PMID 32650452, 2020). "Thus, high CD68+ TAMs infiltrating TS were significantly associated with larger tumor." (PMID 33194645, 2020). "Hence, we used CD68 in combination with CD163 (M2 marker) to show tumor-associated macrophages." (PMID 33061855, 2020). "Thus the expression of IL-33 by the tumours diminished the accumulation of immune suppressive cells and promoted elevated numbers of infiltrating CD68+ tumour-associated macrophages and neutrophils in the metastatic IL-33-expressing tumours compared to unmodified metastatic tumour." (PMID 29440650, 2018). "The current study aims to answer the question if Gal3 expression and the ratio of Gal3 positive cells vs. CD68 positive macrophages in diagnostic biopsies and tumor resection specimens of oscc is associated with histomorphologic parameters (T-, N-, L-, Pn-status, grading) of tumor progression." (PMID 29284429, 2017). "However, the expression of IL-33 by the tumours appeared to prevent the accumulation of these immune-suppressive cells, and promoted intensive infiltration by CD68+ tumour-associated macrophages and neutrophils in IL-33-expressing A9 tumours compared to unmodified A9 tumours." (PMID 27619158, 2016). "Immunofluorescence (IF) staining for CD68 and TMEM119 on brain sections from an independent cohort confirmed that CD68+TMEM119- MDMs densely populated the tumor core, while CD68+TMEM119+ microglia were enriched at the tumor periphery." (PMID 41503214, 2026). "The tumor demonstrated classic histopathological and immunohistochemical features, including CD68 positivity, approximately 10% Ki-67 proliferative index, and osteoclast-like multinucleated giant cells." (PMID 42017075, 2026). "CD68+ macrophages contribute to extracellular matrix remodeling, tumor signaling, and metabolic dysfunction." (PMID 42196186, 2026). "CD4+, CD8+, and CD68+ cell densities at the tumor center and invasive front were quantified using multiplex immunofluorescence imaging." (PMID 41792411, 2026). "Immunohistochemically, tumor cells diffusely expressed cytokeratins, vimentin, CD68, CD163, and EMA, with focal expression of SMA, S-100, calponin, and CD3, but were negative for CD21, CD35, CD1a, ALK, and HHV8." (PMID 42311660, 2026). "Spatial analyses revealed distinct immune cell communities in primary and metastatic PDAC, in which cytokeratin 19 (CK19+) cells clustered differentially with αSMA+, CD3+, and CD68+ cells, depending on the tumor site." (PMID 41418102, 2026). "Most TAMs in the tumor core are double-positive for CD68 and F4/80, but the TAMs at the tumor edge are more F4/80+ than CD68+." (PMID 40745073, 2026). "Multiplex fluorescence staining (PanCK, CD45, CD68) enabled compartment-specific transcriptomic analysis of tumor center regions, immune cell infiltration area, and other stromal regions." (PMID 42220510, 2026). "The panel allowed for identification of DCN, CD4+ T cells, CD8+ T cells, CD20+ B cells, CD68+ macrophages, and PanCK+ tumour cells." (PMID 41392017, 2026). "In the IHC analysis, we found that 7 days after tumor cell transplantation the content of CD68+ macrophages was significantly higher in animals with regenerated spleen than in other groups of animals." (PMID 41522488, 2026). "The distribution of TAMs in the deepest tumor infiltration zone was examined using fluorescent double staining (CD68: macrophages, CD34: vascular endothelial cells)." (PMID 40243510, 2025). "The presence of CD68, a marker for pan-macrophages, in the TME of DLBCL offers valuable insights into the function of tumor-associated macrophages (TAMs) in tumor biology." (PMID 40599139, 2025).